GNAI2 (G protein subunit alpha i2)
Diseases named in the same sentence as GNAI2 in open-access papers (continued):
Sharing a sentence is not in itself a finding about the gene and the disease.
tumor (19 papers, 2013 to 2025). "A recent study evidenced tumor-suppressing GNAI2 mutations leading to β-catenin degradation and consequent decreased cell proliferation in CRC." (PMID 39195201, 2024). "This adds a novel immune-oncological dimension to our findings and suggests a role for GNAI2 in modulating anti-tumor immunity." (PMID 40819057, 2025). "Specifically, the Purinergic genes P2RX1 and GNAI2 have significant roles in promoting the EMT process of tumor cells, while P2RY13 can inhibit the progression of the tumor cell cycle." (PMID 38180750, 2024). "The results showed that G Protein Subunit Alpha I2 (GNAI2) was elevated in tumor samples at the mRNA level, whereas the PSME1 mRNA expression level was significantly reduced in tumor tissues." (PMID 36671532, 2023). "By targeting the G protein (Galphai2, GNAI2), miRNA-30d promotes tumor invasion and metastasis." (PMID 39591208, 2024). "Our lab has previously reported that miR-222-3p could target GNAI2 to inhibit tumor proliferation and target PDCD10 to inhibit cell migration in OC." (PMID 35451651, 2022). "We previously reported that miR-222-3p could inhibit tumor proliferation via targeting GNAI2 in EOC, and lower miR-222-3p expression predicted a worse prognosis." (PMID 32483426, 2020). "We have previously reported that miR-222-3p could inhibit tumor proliferation by targeting GNAI2 in EOC and could also inhibit cell migration." (PMID 32483426, 2020). "We previously reported that miR-222-3p could inhibit tumor cell proliferation by targeting GNAI2 in epithelial ovarian cancer." (PMID 32483426, 2020). "The low expression of GNAI2 in IDC may be one of the reasons for promoting tumor progression." (PMID 36671532, 2023). "This study reveals the tumor-suppressive function of GNAI1, GNAI2, and GNAI3 in COAD through genetic, epigenetic, and miRNA-mediated regulation." (PMID 40819057, 2025). "Furthermore, six tumor progression genes (GNAI2, ODC1, APP, TNFRSF12A, BASP1, and LARP6) and nine migration and metastasis‐related genes (MSN, FLOT1, LAMB3, MYL9, ITGB1, FTH1, TPM4, and PMEPA1), which could explain the invasive characteristics of SCC, were identified." (PMID 40776410, 2025). "Overexpression of GNAI1 and GNAI2 significantly suppressed proliferation, colony formation, and migration in COAD cells, confirming their anti-tumor roles." (PMID 40819057, 2025). "The analysis results showed that the expression levels of Purinergic genes GNAI2, GNAI3, P2RX4, P2RX7, and PANX1 were significantly higher in tumor tissues than in normal tissues, consistent with the mRNA expression results." (PMID 38180750, 2024). "We obtained the protein expression data of Purinergic genes GNAI2, GNAI3, GNAO1, P2RX4, P2RX7, and PANX1 in normal tissues and tumor tissues in the UALCAN database." (PMID 38180750, 2024). "The region located between 3p21.3 and 3p14.3, deleted in both cell sub-lines, contains several established tumor suppressor genes including LTF, TDGF1, WNT5a, and RASSF, as well as candidate tumor suppressors such as CACNA2D3, GNAI2, and SEMA3B." (PMID 23951555, 2013). "This study was designed based on the hypothesis that members of the GNAI gene family (GNAI1, GNAI2, and GNAI3) play tumor-suppressive roles in COAD and that their downregulation may have diagnostic, prognostic, and therapeutic significance." (PMID 40819057, 2025). "In contrast, in pancreatic ductal adenocarcinoma, GNAI2 exerts pro-tumorigenic effects by activating the extracellular signal-regulated kinase (ERK1/2) signaling cascade, thereby enhancing tumor cell proliferation, epithelial-to-mesenchymal transition (EMT), and invasive potential." (PMID 40819057, 2025). "In the analysis, the GNAI2 protein was not significantly or differentially expressed between the normal and tumor tissues." (PMID 37894479, 2023).
tumor (continued). "Given that GNAI2 is involved in the regulation of melanocyte-stimulating hormone (MSH) signaling, which is essential for melanin production, disruption in GNAI2 function may alter MSH responses, reducing melanin synthesis and contributing to skin depigmentation." (PMID 40760343, 2025). "This study demonstrates that GNAI1, GNAI2, and GNAI3 may act as tumor suppressors in COAD." (PMID 40819057, 2025). "GNAI2 expression also correlates with tumor stage independent of cell histology." (PMID 24423449, 2014). "Among all family members, GNAI2 and GNAI3 demonstrated differential expression levels between the GBM tumor and normal tissue samples, whereas GNAI1 was not significantly or differently expressed." (PMID 37894479, 2023).
infection (1 paper, 2018). The state of being infected such as from the introduction of a foreign agent such as serum, vaccine, antigenic substance or organism. "While infection of control Gnai2+/+ cells with wt-Salmonella resulted in strong labeling of deamidated G proteins after 6 h, almost no labeling was observed in Gnai2-/- DCs." (PMID 30102745, 2018).
neurological diseases (1 paper, 2021). "Interestingly, we found that GNAI2 and GNA11 were two mostly shared genes linking profenamine with neurological diseases." (PMID 34131148, 2021).
GNAI2 also shares sentences with these, for which no sentence is quoted: diabetes (2 papers); multiple myeloma (2); adenocarcinoma (1); bladder carcinoma (1); cardiac arrhythmia (1); cervical cancer (1); cleft lip (1); cocaine addiction (1); colon cancer (1); Coronary Artery Aneurysms (1); diffuse large B-cell lymphoma (1); endometrial carcinoma (1); endothelial dysfunction (1); epilepsy (1); essential hypertension (1); glioblastoma (1); inflammation (1); Kawasaki disease (1); keloid (1); liver fibrosis (1); lung adenocarcinoma (1); metabolic disease (1); nephrotic syndrome (1); pituitary adenoma (1); skin melanoma (1); ulcerative colitis (1).